DSPP (dentin sialophosphoprotein)
Diseases named in the same sentence as DSPP in open-access papers (continued):
Sharing a sentence is not in itself a finding about the gene and the disease.
osteoarthritis (1 paper, 2024). A noninflammatory degenerative joint disease occurring chiefly in older persons, characterized by degeneration of the articular cartilage, hypertrophy of bone at the margins and changes in the synovial membrane. "Thus, this study was able to demonstrate that DSPP haplodeficency accelerated the osteoarthritis-like lesions in mandibular condyle." (PMID 38745274, 2024). "The modified Mankin scores showed that the haplodeficency of DSPP could lead to osteoarthritis." (PMID 38745274, 2024).
prostate adenocarcinoma (1 paper, 2016). "Chi square analysis of immunohistochemistry results showed significant upregulation of OPN (X2=25.710/p<0.001), BSP (X2=19.546/p<0.001), and DSPP (X2=8.720/p=0.003) in prostate adenocarcinoma (pAdC)." (PMID 27331624, 2016).
cancer (11 papers, 2009 to 2022). A tumor composed of atypical neoplastic, often pleomorphic cells that invade other tissues. "Several proteins involved in cancer pathways had mutations in more than one patient, the most common being MUC4, GOLGA6L2, DSPP, FOXO6 and HLA-DRB1." (PMID 25605237, 2015). "DSPP and several other members of the Small Integrin Binding Ligand N-linked Glycoprotein (SIBLING) family of extracellular matrix proteins have now emerged as significant molecular tools employed by several cancers to facilitate their progression." (PMID 32630820, 2020). "Dentin sialoprotein phosphoprotein (DSPP), a member of the Small Integrin Binding Ligand N-linked Glycoprotein (SIBLING) and its cognate Matrix Metalloproteinase partner (MMP20), is upregulated in several human cancers." (PMID 32630820, 2020). "DSPP expression increased significantly with tumor stage in all cancers examined." (PMID 30932369, 2019). "Over the past decade, we and others have reported the upregulation of dentin sialophosphoprotein (DSPP), a member of the small integrin binding ligand n-linked glycoproteins (SIBLING) family of extracellular matrix proteins in several human cancers, including OSCCs." (PMID 30002682, 2018). "Notably, DSPP levels were significantly higher in cancer derived cells, PC3 and LNCap, than in the rest of the cell lines." (PMID 27331624, 2016). "A recent in vitro study suggested that the inhibition of endogenous DSPP expression repressed the carcinogenesis features of human oral squamous cells, and the expression of DSPP was recently shown to be upregulated in several cancer tissues." (PMID 25396425, 2014). "Furthermore, it is plausible that other hallmarks of oral carcinogenesis, including cancer cell proliferation and angiogenesis, significantly reduced following DSPP silencing, may also implicate mechanisms involving KLK downregulation." (PMID 32630820, 2020). "Dentin sialophosphoprotein (DSPP), bone sialoprotein (BSP), and osteopontin (OPN) are three members of the Small Integrin-Binding LIgand N-linked Glycoprotein (SIBLING) family of proteins reported to be up-regulated in a number of cancers, including breast, lung, prostate, and OSCCs." (PMID 22410369, 2012). "DSPP is also expressed in non-mineralized tissues including metabolically active ductal epithelia and some cancers." (PMID 20030824, 2009). "Although, the mechanisms of DSPP‐MMP20 interactions in cancers have yet to be fully deciphered, our published data showing a ninefold enrichment of DSPP at the MMP20 promoter in oral cancer cell lines suggest a regulatory role for DSPP in the transcription of MMP20." (PMID 30932369, 2019). "On the bases of these numerous reports linking CSC marker expression with various aspects of cancer biology, it is therefore reasonable to speculate that the changes observed with OCSC following DSPP/MMP20 silencing may be translatable into several anticancer effects." (PMID 30002682, 2018). "Our previous reports also have established that a number of matrix metalloproteinases (MMPs), known to be upregulated in cancers, including OSCC, bind and interact with specific MMPs in biochemical and biologic systems: MMP2 with BSP; MMP3 with OPN; MMP9 with DMP1; and MMP20 with DSPP." (PMID 30002682, 2018). "We also found that six genes (TBP, EP400, DSPP, MUC21, MLLT3, and MUC2) were under negative selection in more than five cancer types." (PMID 28938601, 2017).
tumor (7 papers, 2010 to 2021). "The expression of MMP20 along with DSPP was assessed in several tumor types of breast, colon, prostate, thyroid and cervical region." (PMID 33681393, 2021). "With respect to OSCC, DSPP expression correlated with tumor aggressiveness and prognosis, including tumor recurrence at primary sites." (PMID 30002682, 2018). "Accumulating data are beginning to implicate other family members, notably BSP and DSPP, with roles in specific stages of tumor progression including cell growth, adhesion, migration, and/or metastasis." (PMID 21103065, 2010). "Thus these results indicate that the tumorigenic effect of MMP20/DSPP is mediated by the up-regulation of genes potentially involved in steps leading to tumor development, progression and invasion." (PMID 33681393, 2021). "Indeed, our published studies show that DSPP-silenced OSC2 cells exhibited increased sensitivity to cisplatin-induced apoptosis in tumor cells." (PMID 30002682, 2018). "As a secreted protein DSPP represents an ideal target for a shRNA-mediated silencing, and by analyzing the functional effects of DSPP-silencing in OSC2, we show that DSPP-silencing down-regulates key proteins involved in tumor cell proliferation, angiogenesis, and local invasion." (PMID 21103065, 2010). "Other noteworthy genes included DSPP, PER3, MTCH2, and KRT18, all have been reported with important roles in tumor formation and development." (PMID 32231683, 2020). "Based on these findings we hypothesize that DSPP plays a significant role in migration and invasiveness within OSCC microenvironment to at least aid local spread of tumor." (PMID 21103065, 2010). "Our present data indicate that DSPP suppression alone, while resulting in G0/G1 arrest, does not increase tumor cell death by apoptosis in OSC2 cells." (PMID 21103065, 2010). "DSPP-silenced OSC2 cells showed altered cell morphology, reduced viability, decreased colony-formation ability, decreased migration and invasion, G0/G1 cell-cycle arrest, and increased tumor cell sensitivity to cisplatin-induced apoptosis." (PMID 21103065, 2010). "Furthermore, DSPP silencing in OSCC cell line decreased notable hallmarks of oral tumorigenesis, such as cell viability, invasion and migration, colony-formation, G0/G1 cell cycle arrest, while increasing tumor cell sensitivity to cisplatin-induced apoptosis." (PMID 30002682, 2018). "We employed immunohistochemistry (IHC), immunofluorescence (IF), and in situ proximity ligation assay (iPLA) to survey five common human neoplasms, along with their normal tissue/nonneoplastic counterpart, for the expression of MMP20 and DSPP, using TMA, lysates, and cell lines." (PMID 30932369, 2019). "In this study, we aimed to correlate the expression of DSPP, OPN and BSP as well as three SIBLING-partners, matrix metalloproteinase-2 (MMP-2), matrix metalloproteinase-3 (MMP-3), and matrix metalloproteinase-9 (MMP-9), at histologically-negative margins of OSCCs with tumor recurrence." (PMID 22410369, 2012).
epithelial neoplasm (1 paper, 2019). A benign or malignant neoplasm that arises from and is composed of epithelial cells. "In summary, we report MMP20 and DSPP expression and interaction in five common human epithelial neoplasms and their normal tissue counterparts: the breast, colon; cervix; prostate; and thyroid." (PMID 30932369, 2019). "Our study is based on the hypothesis that DSPP and its cognate MMP20 partner are upregulated in some human epithelial neoplasm where co‐localization and interaction, seen in OSCC, may also take place." (PMID 30932369, 2019).
infection (1 paper, 2022). The state of being infected such as from the introduction of a foreign agent such as serum, vaccine, antigenic substance or organism. "We used DSPP as a marker to confirm that there was reduced odontoblast differentiation and mineralization in cultures with Tgbr2 deletion in the DPCs due to Ad-Cre infection." (PMID 35265620, 2022).
DSPP also shares sentences with these, for which no sentence is quoted: periodontitis (2 papers); adenocarcinoma (1); adenoma (1); Alport syndrome (1); Alstrom syndrome (1); amelogenesis imperfecta (1); Arrhythmia (1); benign prostatic neoplasms (1); biotinidase deficiency (1); chronic periodontitis (1); chronic prostatitis (1); Clouston syndrome (1); congenital sensorineural deafness (1); dental caries (1); dentinogenesis imperfecta 1 (1); erythrokeratodermia variabilis (1); Fibroadenoma (1); genetic disorders (1); Hashimoto thyroiditis (1); Immunodeficiency (1); invasive ductal carcinoma of (1); malocclusion (1); meningioma (1); microtia (1); Onset (1); oral premalignant lesions (1); papillary thyroid carcinoma (1); periodontal disease (1); pituitary adenomas (1); primary immunodeficiency (1).
A further 4 diseases each share a sentence with DSPP in 1 paper.